ALPG (alkaline phosphatase, germ cell)
Description:
Alkaline phosphatase that can hydrolyze various phosphate compounds.
Synonyms: GCAP; ALPPL; ALPPL2
Tractability: Small molecule: it belongs to a druggable protein family. Antibody: its Gene Ontology location is reachable by antibodies, with high confidence; UniProt places it where antibodies can reach, with medium confidence; UniProt predicts a signal peptide or a membrane-spanning region; the Human Protein Atlas places it where antibodies can reach. PROTAC: ubiquitination databases record sites on it; a small molecule that binds it is known.
Target class: Enzyme; Phosphatase
Gene: Protein-coding gene on chromosome 2 (232,406,844 to 232,410,714, forward strand). Ensembl gene ENSG00000163286.
Subcellular location: Cell membrane
Subcellular location (Human Protein Atlas): Plasma membrane
Pathways (Reactome):
Metabolism of proteins: Post-translational modification: synthesis of GPI-anchored proteins
Gene Ontology:
Molecular function: alkaline phosphatase activity; phosphatase activity
Cellular component: extracellular region; plasma membrane
Genetic constraint (gnomAD): Loss-of-function variants: 32 observed, 38.97 expected, observed/expected ratio (o/e) 0.82, 90% interval 0.62 to 1.1. The upper end of that interval is the gene's LOEUF score, 1.1, which puts it in group 4 of 6, group 1 being the genes least tolerant of losing a copy. Missense variants: 503 observed, 554.54 expected, observed/expected ratio (o/e) 0.91, 90% interval 0.84 to 0.98. Synonymous variants: 234 observed, 231.26 expected, observed/expected ratio (o/e) 1.01, 90% interval 0.91 to 1.13.
Homologues: Orthologues: chimpanzee ALPG (99% identical), macaque ALPP (92% identical), dog ALPI (77% identical), mouse Alpi (74% identical), mouse Akp3 (74% identical), mouse Alppl2 (73% identical), rat Alpg (73% identical), rat Alpp (73% identical), rat Alpi (72% identical), rat Akp3 (72% identical), tropical clawed frog alpi (59% identical), zebrafish alpi.2 (55% identical), and 13 more. Paralogues in human: ALPP (97% identical), ALPI (86% identical), ALPL (53% identical).
Diseases named in the same sentence as ALPG in open-access papers:
ALPG is named in the same sentence as 21 diseases in open-access papers, as found by Europe PMC text mining. Sharing a sentence is not in itself a finding about the gene and the disease.
ALPG shares sentences with these, for which no sentence is quoted: tumor (13 papers); mesothelioma (7); pancreatic cancer (7); ovarian carcinoma (5); cancer (3); seminoma (2); adenocarcinoma (1); atherosclerosis (1); cystic neoplasm (1); germ cell neoplasms (1); glioblastoma (1); hematopoietic cancers (1); lung adenocarcinoma (1); lung carcinoma (1); pancreatic ductal adenocarcinoma (1); pancreatitis (1); schizophrenia (1); squamous cell carcinoma (1); squamous cell lung carcinoma (1); testicular cancer (1); testicular germ cell tumours (1).